MDK (midkine)
Diseases named in the same sentence as MDK in open-access papers (continued):
Sharing a sentence is not in itself a finding about the gene and the disease.
tumor (continued). "In a similar context, MDK-inhibition could be explored in the prevention and treatment of tumor metastasis in HNSCC and add synergy to PD1-blockade which is the current standard of care in metastatic HNSCC." (PMID 36973261, 2023). "Besides, high midkine expression was positively correlated with advanced tumor stages and poor overall-survival of HCC patients." (PMID 36906597, 2023). "In addition, forced midkine expression apparently attenuated the suppression of anti-PD-1 antibody on HCC tumor growth." (PMID 36906597, 2023). "Hence, we found that miR-1275 acted as a tumor suppressor by targeting MDK to reduce the properties of CSCs by inactivation of PI3K/AKT signaling pathway." (PMID 36594100, 2023). "Moreover, midkine overexpression stimulated immunosuppressive MDSC accumulation in HCC tumor microenvironment, while midkine inhibition exhibited opposite effects." (PMID 36906597, 2023). "Uncovering the exact signals that drive MDK expression and its transduction through its various binding partners in the tumor microenvironment is therefore of highest interest to identify novel therapeutic strategies that overcome tumor resistance." (PMID 38098484, 2023). "The enriched MDK–NCL signal could serve as a sign of CAF activation to stimulate downstream pathways for promoting tumour invasion, and therefore may be a potential early biomarker of ESCC progression." (PMID 36855810, 2023). "The enriched MDK–NCL signal could serve as a sign of CAF activation to stimulate downstream pathways for facilitating tumour invasion, and thus may be a potential early biomarker of ESCC progression." (PMID 36855810, 2023). "In these lines, MDK might be a candidate for cancer vaccine development, as it has been shown that MDK-primed cytotoxic T cells are able to lyse tumor cells." (PMID 38098484, 2023). "In these lines, MDK/ALK signaling is especially involved in neoplastic diseases, as it initiates, for example, an autocrine growth and survival signal via the suppression of caspases, as well as the enhancement of B-cell lymphoma-2 (Bcl-2), an anti-apoptotic protein and oncogene." (PMID 38098484, 2023). "MDK expression was found to be upregulated in numerous human neoplasms." (PMID 38250070, 2023). "Our study provided inhibition of AT1R by IRB may reduce tumor progression in MDK-expressed HNSCC patients." (PMID 37743493, 2023). "MDK expression has been determined in blood, urinary, and tumor tissues of cancer patients." (PMID 36721112, 2023). "Recombinant MDK was used to treat PDAC cells to assess the effects of MDK on tumor progression." (PMID 37524695, 2023). "As MDK/LRP1 signaling contributes to anchorage-independent tumor cell growth, its disruption might be a promising cancer treatment approach, along with MDK-TRAP and polyclonal antibodies." (PMID 38098484, 2023). "Similar mechanisms of MDK may contribute to the development and pathogenesis of neoplastic diseases, where neurons, microglia, macrophages, and T cells in the tumor microenvironment control formation, growth, and progression of malignant solid tumors." (PMID 38098484, 2023). "Emerging evidences indicate that midkine is vital for hypoxia-driven tumor angiogenesis." (PMID 36906597, 2023). "Based on the results of our study, CDK1/tumor cluster cells may release MDK to promote the proliferation of tumor cells and mediate the exhaustion of immune cells in an autocrine or paracrine manner." (PMID 36950551, 2023). "Compared with the IgG isotype control, tumor growth, volume and weight of subcutaneous Hepa 1-6 tumors were significant reduced by anti-PD-1 antibody, however this effect was largely abolished by midkine overexpression." (PMID 36906597, 2023). "In neoplastic diseases, MDK promotes tumor growth, differentiation, and therapy-resistance." (PMID 38098484, 2023).
tumor (continued). "Finally, we found that the pleiotropic growth factor/cytokine Midkine (MDK) was upregulated in fibroblasts of primary tumors and potentially promoted their proliferation, further blocking the migration of tumor cells from the TME." (PMID 36438481, 2022). "In primary cSCC, MDK was highly expressed in fibroblasts and could promote their proliferation and block the migration of tumor cells, while in recurrent cSCC, the high expression of MDK in TSKs promoted their proliferation and metastasis." (PMID 36438481, 2022). "When fibroblasts highly express MDK, it may promote fibroblast replication and block the proliferation and metastasis of tumor cells through cellular interactions, thus avoiding tumor recurrence." (PMID 36438481, 2022). "Conversely, TSKs may acquire proliferative or EMT capacity in recurrent tumor tissues by expressing MDK, which then mediates tumor recurrence." (PMID 36438481, 2022). "Attenuation of the pro-metastatic activity of IFN-γ may help to augment its anti-tumor effects during cancer treatment, thus our data propose a combined use of MDK inhibitors in IFN-γ-based cancer therapies." (PMID 35747815, 2022). "Based on the IHC staining, MDK expression was upregulated in recurrent cSCC and was positively correlated with two EMT-associated genes, VIM and TGFB1, possibly playing a critical role in facilitating the proliferation and metastasis of tumor cells." (PMID 36438481, 2022). "IGF-1R knockdown via lentivirus-mediated RNAi could remarkably suppress tumor cell growth and apoptosis through attenuating the expression level of midkine in HCC cells." (PMID 33768092, 2021). "Moreover, patients with MDK-elevated HCC have higher amount of circulating tumor cells (CTCs) and significantly higher recurrence rate and shorter RFS." (PMID 33562077, 2021). "Moreover, histological analyses demonstrated that BO‐110 resulted in a potent abrogation of MDK expression in vivo, both in xenografts generated by human cell lines and from tumor biopsies." (PMID 34762341, 2021). "Specifically, we set to test two clinically relevant aspects of the antitumoral activity of BO‐110: (i) organ‐dependent efficacies (namely, tumor vs lymph node and visceral sites), and (ii) the possibility of exploiting MDK as a biomarker of response in liquid biopsies (blood samples)." (PMID 34762341, 2021). "Moreover, it is important to consider that VEGFR3 and MDK are deregulated in a variety of tumor types and inflammatory diseases." (PMID 34762341, 2021). "In particular, our findings revealing circulating MDK as a biomarker that reflects reduced tumor burden after BO‐110 treatment may prove useful to assess the antitumoral activity of this compound beyond less specific IFN‐associated markers." (PMID 34762341, 2021). "The frequent upregulation of MDK across tumor types may reflect that the gene’s promoter contains a hypoxia response element." (PMID 34556138, 2021). "Guided by these results, we proceeded to a mechanistic study that ultimately uncovered a dual IFN‐dependent repressive role of BO‐110 on tumor cells (inhibiting MDK expression and secretion) and on lymphatic endothelial cells (repressing on Vegfr3 mRNA levels)." (PMID 34762341, 2021). "In addition, MDK can activate the Akt signalling pathway in tumour and endothelial cells and promote VEGFR3 expression through mTOR signalling pathway to promote tumorigenesis and development." (PMID 34759262, 2021). "In addition, xenoplastic transplantation of stem cells overexpressing MDK elevated the tumour growth rate and the weight of the tumour at 28 days." (PMID 32592428, 2020). "We may also speculate that MDK might enter into the blood circulation from tumor tissues, and that plasma MDK levels could be clinically relevant in patients with IBD-associated colonic malignancy." (PMID 31905498, 2020). "Several promising studies described the use of midkine (MK) as a tumor marker." (PMID 31984657, 2020).
tumor (continued). "Notably, the MDK-expression group promoted tumor volume and also micro-invasiveness of cancer cells measured via H&E and anti-T antigen staining." (PMID 32847073, 2020). "However, MDK siRNA or iMDK, which is an MDK inhibitor, decreased endothelial cell migration, tumor promotion, and metastasis both in vitro and in vivo." (PMID 32847073, 2020). "Midkine (MK) is a growth factor and a promising tumor marker for different tumor entities." (PMID 31984657, 2020). "Besides, Midkine (MDK) was described as often upregulated in the tumor microenvironment of SCC tumor tissues and cell lines (SCC4, OSCC3, HSC3, and CAL27)." (PMID 32438606, 2020). "Interestingly, MDK is of significance in human tumour processes and in biological processes such as enhancement of fibrinolytic activity, induction of chemotaxis and angiogenesis and inhibition of apoptosis." (PMID 32592428, 2020). "Interestingly, we observed that the sensitivity to MDK neutralization across 19 different GBM tumor spheres was diverse." (PMID 31811117, 2019). "This study showed the therapeutic efficacy of antagonizing MDK in GBM tumor spheres." (PMID 31811117, 2019). "The spatial expression of MDK was closely correlated with that of SOX2 in a GBM tumor specimen." (PMID 31811117, 2019). "Additionally, the level of MDK was upregulated in NPC tumor samples and was positively correlated with microvessel density." (PMID 30001734, 2018). "SPs may also participate in tumour immunity, for example the presequence from midkine (a protein contributing to tumour progression) contains epitopes that are recognized by CD4+ T cells." (PMID 30469512, 2018). "Furthermore, Immunohistochemistry (IHC) and in situ hybridization (ISH) was used to detected miR-9, CD31 and MDK expression in human NPC tumor samples." (PMID 30001734, 2018). "Furthermore, midkine mediated tumor cell adhesion to LECs and promoted tumor colonization in distant organs." (PMID 29527513, 2018). "Furthermore, in in vitro and in vivo assays, knockdown of midkine resulted in significant sensitivity to anoikis, decreased cell survival and significantly decreased tumor occurrence rate." (PMID 28430645, 2017). "The serum midkine levels were positively correlated with midkine expression in tumor tissues." (PMID 27974680, 2016). "Another study demonstrated that serum MDK is elevated in most HCC and may have a diagnostic role in AFP-negative and early stage tumours." (PMID 27219517, 2016). "Thus, the serum midkine levels were an appropriate substitute for midkine expression in tumor tissues from patients with NSCLC." (PMID 27974680, 2016). "Interestingly, previous reports have also shown high expression of MDK in advanced tumours which correlated to serum levels and tumour progression." (PMID 26998479, 2015). "Interestingly, surface NCL is also a receptor for various molecules including cytokines (like midkine and pleiotrophin), vascular-targeting factors (endostatin and tumour-homing peptide F3) and some glycosaminoglycans." (PMID 25938538, 2015). "Hence, the aim of our study was to examine protein level of midkine in tumor versus normal colorectal tissue and relate it to the disease progression, tumor location, and circulating levels of cytokine." (PMID 22562257, 2012). "Midkine overexpression is common among solid tumors, as it may facilitate tumor cell proliferation, survival, and migration, and enables invasion." (PMID 22562257, 2012). "Except for one case, midkine was higher in tumor than in normal tissue, i.e., in 98 % of the cases." (PMID 22562257, 2012). "Not only we found midkine to be expressed more profusely in noncancerous rectal than colonic tissue, but also tumor location determined midkine association with the disease stage." (PMID 22562257, 2012). "Taken together, these results may imply that elevated midkine expression can contribute to early stages of colon carcinogenesis by facilitating tumor cell proliferation." (PMID 22562257, 2012).
tumor (continued). "The expression of these genes may, at least in part, explain the increase in invasiveness following 5-Aza-2-deoxycytidine treatment, as both sox-2 and midkine may play roles in tumor progression." (PMID 20019818, 2009). "Midkine expression in various malignant tumours is higher than that in normal tissues." (PMID 18682710, 2008). "Midkine levels in blood may thus become a useful tumour marker for predicting prognosis of cancer patients." (PMID 18682710, 2008). "Midkine has the apparent ability to promote vascularisation and fibroblast growth, suppress apoptosis, and induce cell migration, and is thought to be involved in carcinogenesis and tumour progression." (PMID 17622248, 2007). "Finally, integrating additional multi-omics approaches, such as proteomics and metabolomics, could provide a more comprehensive understanding of the complex regulatory roles of MDK-NCL signaling in tumor progression and immune evasion." (PMID 40396179, 2025). "Interestingly, we found that the ligand-receptor pair MDK - NCL between tumor cells and immune cells was significantly up-regulated in MLN, suggesting that this pathway may play an important role in tumor immune responses." (PMID 41249133, 2025). "Additionally, elevated expression of immune checkpoint genes (e.g., PDCD1 and CTLA-4) in the high MDK-NCL group suggests that this pathway might promote immune evasion by enhancing the tumor’s dependence on checkpoint mechanisms." (PMID 40396179, 2025). "Furthermore, this data suggests that MDK may shape the tumor microenvironment by inhibiting immune cells and modulating stromal cells via MDK-NCL." (PMID 40429950, 2025). "The fact that MDK was highly expressed at IHC level also in RMP led us to hypothesize that this protein could be involved in tumor progression as well as in a more general mechanism of proliferation of mesotheliocytes, likely induced by inflammatory conditions." (PMID 39300217, 2024). "Besides its important role during development and differentiation of various cell types, MDK has been shown to be upregulated in various pathological conditions in the periphery and the CNS, reaching from neoplastic diseases to inflammatory diseases and injuries." (PMID 38098484, 2023). "Moreover, the pro-tumor functional role of Schwann cells could be greatly compromised by neutralizing antibodies against MDK." (PMID 37524695, 2023). "Moreover, CTGF+ CAFs may further impact tumor-associated macrophages (TAMs) by the M2-type macrophages through ligand-receptor molecules, such as SPP1-CD44, PTN-NCL, and MDK-NCL." (PMID 35894206, 2022). "This approach revealed that MDK could indeed be detected in blood, reflecting tumor size." (PMID 34762341, 2021). "Therefore, pharmacological blockade of MDK may have the added value of not only interfering with tumor neolymphangiogenesis and metastasis, but also impinging on the immune milieu." (PMID 34762341, 2021). "However, MDK knock down suppresses the pro-tumor effect of hypoxia-induced MDK in vitro." (PMID 32847073, 2020). "Furthermore, the relative increase in the transcriptional and translational expression level of insulin-like growth factor-binding protein 7 (IGFBP7), midkine (MDK), and beta-2-microglobulin (B2M) genes was observed in remnant tumor cells after tipifarnib treatment." (PMID 32460812, 2020). "Moreover, the MDK inhibitor decreased tumor progression, metastasis, and angiogenesis in vivo." (PMID 32847073, 2020). "Despite inhibition of IGFBP7 and MDK may be a useful adjunct to co-targeting tumor cells and CAFs in patients with MyoCAF-rich tumors, few targeting agents are currently available for these molecules, which led us to focus on TME that showed immunosuppressive features." (PMID 32460812, 2020).
tumor (continued). "In light of the patient survival curves stratified by CD8 and CCL5 tumor expression, these T cell–microglia interactions may be particularly relevant to LGGs, where MDK/CCL4-independent mechanisms involving CD8+ T cells and microglia result in CCL5 support of tumor growth." (PMID 32358581, 2020). "Notably, EHMK‐51‐35 carrier cells infected with AdE3‐midkine or co‐infected with AdE3‐midkine and Ad‐mGM‐CSF induced 80% or 100% of complete tumor reduction, respectively, which increased the survival rates significantly compared to A549 carrier cells (p < 0.05)." (PMID 30548997, 2019). "However, EHMK‐51‐35 carrier cells infected with AdE3‐midkine or co‐infected with AdE3‐midkine and Ad‐mGM‐CSF induced 20% or 60% of complete tumor reduction, respectively, which increased the survival rates significantly compared to controls and A549 carrier cells (p < 0.05)." (PMID 30548997, 2019). "Importantly, we show that MDK is elevated in pre-clinical tumour samples and therefore may have a role in the early detection of HCC." (PMID 27219517, 2016). "However, further analysis revealed that midkine expression differed with respect to tumor location." (PMID 22562257, 2012). "MDK may promote angiogenesis in vivo and therefore provide further support for tumor growth." (PMID 18275606, 2008). "Serum midkine concentrations will allow us to predict prognosis because, in the presence of highly elevated concentrations, we would use a larger surgically margin when removing a tumour and would perform chemotherapy and/or radiotherapy before or after the operation with better results." (PMID 18682710, 2008). "MDK also plays a key role in tumor progression by promoting angiogenesis and epithelial-to-mesenchymal transition (EMT), mechanisms that enhance tumor invasiveness and metastasis." (PMID 40500394, 2025). "MDK has been shown to activate the PI3K and MAPK pathways, promoting cell survival, proliferation, and anti-apoptotic activity in tumor cells." (PMID 40500394, 2025). "Our analysis also identified a highly enriched ligand-receptor pair MDK - NCL, contributing to communication among HGSOC tumor cells." (PMID 40036264, 2025). "In this study, for the first time, we found increased s‐MDK expression levels in patients with SCLC and observed a correlation between increased s‐MDK levels and SCLC tumor burden." (PMID 40620228, 2025). "Our results showed that MED6-positive tumor cells exhibited more significant activity in interactions with stromal and immune cells via secreted signals like SEMA, MDK, and SPP1." (PMID 40302793, 2025). "MIF was predicted to interact with CD8+ T cells through the CD74 receptor and MDK with NK cells through the SORL1 receptor, with interactions with tumor cells demonstrating the highest predicted probability." (PMID 39908652, 2025). "In both the TCGA-LUAD cohort and in-house cohort, MDK and NCL were significantly upregulated at the mRNA and protein levels in tumor samples compared to normal tissues." (PMID 40396179, 2025). "Research has demonstrated that the MDK-NCL axis facilitates the formation of an immunosuppressive microenvironment, thereby promoting immune evasion by tumor cells and contributing to tumor progression." (PMID 40396179, 2025). "Analysis of bulk transcriptomic data from the TCGA-LUAD cohort revealed that MDK and NCL expression levels were significantly higher in tumor samples compared to control samples." (PMID 40396179, 2025). "Our findings shed light on the mechanisms by which the MDK-NCL pathway contributes to immune suppression and tumor immune evasion." (PMID 40396179, 2025). "Our study highlights the critical role of the MDK-NCL axis in LUAD immune evasion and tumor progression, providing a theoretical basis for targeting this pathway as a novel therapeutic strategy." (PMID 40396179, 2025).